TAS2R38 (taste 2 receptor member 38)
Diseases named in the same sentence as TAS2R38 in open-access papers (continued):
Sharing a sentence is not in itself a finding about the gene and the disease.
gastric cancer (7 papers, 2016 to 2025). A primary or metastatic malignant neoplasm involving the stomach. "In contrast, SNPs within TAS2R38 and TAS1Rs were found to be associated with an increased gastric cancer risk in the Korean population." (PMID 38673029, 2024). "The results of the present study suggest interesting associations surrounding TAS2R38 bitter taste receptor gene and gastric cancer risk; however, some limitations exist." (PMID 27245112, 2016). "Although we investigated a myriad of foods and consumer goods, other foods and genes linked to TAS2R38 may contribute to gastric cancer susceptibility." (PMID 27245112, 2016). "The present study examined whether TAS2R38 genetic variants influence dietary intake and whether they are associated with the risk of gastric cancer in Koreans." (PMID 27245112, 2016). "Given the taste sensitivity-diet-disease risk hypothesis, differential taste sensitivity due to TAS2R38 genetic variants may influence dietary intake and thus modify the risk for gastric cancer." (PMID 27245112, 2016). "However, little is known about the association between TAS2R38 polymorphisms and gastric cancer susceptibility." (PMID 27245112, 2016). "However, because little evidence is available to support those putative correlations, larger epidemiological studies and further investigations are required to verify the underlying mechanisms for the TAS2R38-gastric cancer relationship." (PMID 27245112, 2016). "The present case-control study examined the influence of TAS2R38 polymorphisms on food intake and determined whether they predict gastric cancer risk in Koreans." (PMID 27245112, 2016). "Therefore, the association between TAS2R38 variants and these factors may be related to predisposition to gastric cancer." (PMID 27245112, 2016). "Therefore, alterations in immune responses and/or nitric oxide production related to TAS2R38 variants may modify gastric cancer risk if TAS2R38 mediates such defence mechanisms in the gastrointestinal mucosal epithelia." (PMID 27245112, 2016). "The chi-square tests revealed significant differences in the distribution of TAS2R38 genotype and diplotype depending on gastric cancer phenotype." (PMID 27245112, 2016). "A total of 1,580 subjects, including 449 gastric cancer cases, were genotyped for TAS2R38 A49P, V262A, I296V and diplotypes." (PMID 27245112, 2016). "For instance TAS2R38 SNPs were found to be associated with risk of developing CRC in two different populations of Caucasian origin, while SNPs within TAS2R38 and TAS1Rs were associated with increased risk of gastric cancer." (PMID 28915899, 2017). "In summary, the PAV/AVI diplotype of the TAS2R38 gene increased the risk for gastric cancer, but genetic variation did not influence dietary intake." (PMID 27245112, 2016). "Statistical analyses provided evidence that TAS2R38 genetic variants are clearly associated with gastric cancer risk, although the variants did not influence dietary intake." (PMID 27245112, 2016). "Therefore, starting with the stomach, a case–control study in a Korean population showed an increased gastric cancer risk (OR—1.513; 95% CI—(1.148, 1.994); p = 0.001) associated with the PAV/AVI diplotype of TAS2R38, which evokes an intermediate bitter taste sensitivity to PROP and PTC." (PMID 34885005, 2021). "Findings suggest that TAS2R38 may be associated with the risk for gastric cancer in Koreans, although the TAS2R38 diplotype did not influence dietary intake." (PMID 27245112, 2016). "The study also investigated whether TAS2R38 variants are associated with the risk for gastric cancer either dependent or independent of dietary intake." (PMID 27245112, 2016). "However, to the best of our knowledge, no study has examined the TAS2R38-diet association in gastric cancer risk." (PMID 27245112, 2016).
gastric cancer (continued). "A similarly negligible influence of bitterness genetic variants on food intake was observed in our earlier study on gastric cancer and TAS2R38; in that study, the genetic variations had no significant influence on the population's dietary intake." (PMID 28423504, 2017). "The findings showed that the TAS2R38 diplotype did not predict the dietary intake of the examined foods, alcohol consumption or tobacco smoking, regardless of gastric cancer phenotype." (PMID 27245112, 2016). "Unlike previous studies, our data suggested that the heterozygous TAS2R38 diplotype (PAV/AVI), not the homozygous AVI/AVI genotype, increased the risk for gastric cancer." (PMID 27245112, 2016). "When the subjects were stratified based on gastric cancer phenotype, again, TAS2R38 diplotype did not predict dietary or alcohol intake or cigarette smoking (data not shown)." (PMID 27245112, 2016).
colorectal cancer (6 papers, 2011 to 2024). A primary or metastatic malignant neoplasm that affects the colon or rectum. "It has been identified that TAS2R38 genetic variability haplotypes have a potential link to colorectal cancer (CRC) risk in two distinct Caucasian populations." (PMID 38673029, 2024). "Associations of TAS2R38 tagging polymorphisms with colorectal cancer risk." (PMID 21674048, 2011). "Associations of the TAS2R38 common diplotypes with colorectal cancer risk." (PMID 21674048, 2011). "In the second study of colorectal cancer, the reported results for TAS2R38 and CA6 were opposite to our current observations, and congruent with our initial hypotheses." (PMID 38687739, 2024). "In contrast to this study, in a case–control study on Caucasians, a higher risk for colorectal cancer (OR—1.34; 95% CI—(1.12, 1.61); p = 0.001) was found for non-tasters by comparing all the diplotypes of TAS2R38 linked to non-tasting phenotypes, with the diplotypes eliciting tasting phenotypes." (PMID 34885005, 2021). "Effects on the dietary intake due to genetic variations within the TAS2R38 gene could also not be found in a case–control study in an Asian population, but carrying the AVI/AVI diplotype was associated with a lower risk of colorectal cancer (OR—0.74; 95% CI—(0.56, 0.99); p = 0.021)." (PMID 34885005, 2021).
COVID-19 (6 papers, 2022 to 2025). A disease caused by infection with severe acute respiratory syndrome coronavirus 2. "Nevertheless, few studies have been conducted on the associations between TAS2R38 and COVID-19 severity and prognosis, and with inconsistent outcomes." (PMID 40280971, 2025). "This study builds upon prior studies assessing TAS2R variants and COVID-19 outcomes, with a specific focus on TAS2R38." (PMID 41153757, 2025). "Our results show for the first time, to our knowledge, that cg25481253 methylation level, a CpG site located in the coding region of TAS2R38, is positively associated with COVID-19 severity during infection." (PMID 40280971, 2025). "This is a retrospective study on a cohort of PCD subjects to evaluate the prevalence of COVID-19 in the last four years and a possible correlation between some clinical features of COVID-19 and polymorphisms of the taste bitter receptor TAS2R38." (PMID 39201321, 2024). "On the other hand, TAS2R38 DNAm in post-COVID-19 participants of the second group, i.e. at the time when there was not any active disease, the ∆Ct mean values were associated with the TAS2R38 genotype of participants (H = 8.514, P = 0.0142, Kruskal-Wallis test)." (PMID 40280971, 2025). "However, it is worth noting that prior to correcting for multiple statistical testing, the present study observed some associations between TAS2R38 diplotypes and self-reported experience of certain COVID-19 symptoms related to the sinuses and throat." (PMID 38409357, 2024). "TAS2R38 may be relevant in coronavirus disease 2019 (COVID-19), but research findings are inconsistent." (PMID 38409357, 2024). "The TAS2R38 DNAm profiling was also carried out in a second group of 33 post-COVID-19 participants to analyze the effect of SARS-CoV after the cessation of the exposition to the virus." (PMID 40280971, 2025). "In conclusion, our results clearly indicate the involvement of TAS2R38 DNAm alteration in COVID-19 severity and suggest a role of the methylation changes at cg25481253 in the regulation of the TAS2R38 expression." (PMID 40280971, 2025). "Our results showed a positive relationship between TAS2R38 DNAm levels and disease severity in the COVID-19 patients and a return to a normal state after the infection." (PMID 40280971, 2025). "At first, we analyzed TAS2R38 DNAm profiling in a group of 44 COVID-19-positive patients and 7 participants after the infection (post-COVID-19), who were also included to evaluate the DNAm reversibility after the cessation of the exposition to infection." (PMID 40280971, 2025). "Given the limited number of COVID-19 cases identified in the present study along with the biological plausibility of a role of TAS2R38 in innate immunity, these observations are worth reporting (with caution) to inform future research in this area." (PMID 38409357, 2024). "A careful examination of prior research examining TAS2R38 (or its phenotypic expression) and COVID-19 is needed to properly situate the results reported presently." (PMID 38409357, 2024). "To date, still little is known about TAS1Rs’ role in mediating SARS-CoV-2 immune response, while a few studies have investigated the relationship between TAS2R38 activity and COVID-19 symptom severity, with variable results." (PMID 38398728, 2024). "Our results uncouple the direct genetic contribution of rs10246939, rs1726866 and rs713598 on COVID-19, calling for caution when proposing a treatment based on TAS2R38 phenotypes." (PMID 35513681, 2022). "Nevertheless, the major strength of this study is that this is the first time that polymorphisms of TAS2R38, in particular, haplotypes PAV/AVI and AVI/AVI, were investigated in relation to a possible greater prevalence or poorer outcome of COVID-19 in PCD patients." (PMID 39201321, 2024).
COVID-19 (continued). "Furthermore, the role of TAS2R38 in innate immunity in response to pathogens of the respiratory tract may be supported by recently reported associations between TAS2R38 haplotypes (or T2R38 phenotypes) and coronavirus disease 2019 (COVID-19) infection and symptoms, although evidence is mixed." (PMID 38409357, 2024). "In conclusion, our findings unequivocally demonstrate that TAS2R38 DNAm profiling is crucial for understanding the role of the taste TAS2R38 receptor in COVID-19 severity and might suggest a role of the methylation changes at cg25481253 in the regulation of the TAS2R38 expression." (PMID 40280971, 2025). "Therefore, the common TAS2R38 haplotypes studied in this present investigation appear not to be linked with COVID-19 susceptibility/severity." (PMID 38409357, 2024). "Moreover, TAS2R38 has relatively low expression in extra-oral tissues, suggesting that other TAS2R genes with higher expression in extra-oral tissues may have a stronger association with COVID-19 outcomes." (PMID 41153757, 2025). "Our present findings suggest that subjects with PCD may not be at increased risk of COVID-19 and/or of severe outcomes and that the different haplotypes of the gene codifying for the bitter taste receptor TAS2R38 do not seem to correlate with a propensity to SARS-CoV-2 infection." (PMID 39201321, 2024). "Findings from the present study suggest that common TAS2R38 haplotypes are not related to COVID-19 susceptibility or symptoms, but additional research is warranted to determine whether the haplotypes or related phenotypes are relevant in viral infection symptomatology." (PMID 38409357, 2024). "Data from the CLSA COVID-19 Questionnaire and Seroprevalence sub-studies were utilized with CLSA genetic data for common TAS2R38 haplotypes related to bitter taste sensitivity." (PMID 38409357, 2024). "Our observations of a general lack of relationship between TAS2R38 haplotypes and COVID-19 outcomes are supported by GWAS literature, which to our knowledge have not identified TAS2R38 as a locus of interest for COVID-19 infection or severity." (PMID 38409357, 2024). "Therefore, this study aims to deepen the relationship between COVID-19 symptom presence/severity and TAS1R and TAS2R38 (TAS2Rs member) genetic variations in a cohort of 196 COVID-19 patients." (PMID 38398728, 2024). "Likewise, to the best of our knowledge, the methylation pattern of TAS2R38 in nasopharyngeal and/or saliva samples of COVID-19 patients has not been analyzed." (PMID 40280971, 2025).
breast carcinoma (3 papers, 2017 to 2024). "In our study, we did not observe any statistically significant associations between diplotypes in TAS2R38 gene and breast cancer risk." (PMID 38687739, 2024). "Associations of the TAS2R38 and CA6 with breast cancer in combined groups: Polish women in Poland and Polish immigrant women in USA." (PMID 38687739, 2024). "Associations of the TAS2R38 and CA6 with breast cancer in Polish immigrant women in USA." (PMID 38687739, 2024). "To examine the relationship between risk of breast cancer and TAS2R38 and CA6 gene individually and for the joint genotype we ran logistic regression to obtain odds ratios for breast cancer status for individual diplotypes of the TAS2R38 and individual genotypes of the CA6 gene." (PMID 38687739, 2024). "Associations of the TAS2R38 and CA6 with breast cancer in Polish women in Poland." (PMID 38687739, 2024). "For the combined genes TAS2R38 and CA6, the genotype AVI/AVI+G* (non-tasters), relative to the reference group of PAV/*+A/A (tasters) showed a statistically significant association with breast cancer status (OR = 1.77;95% CI 1.47–2.74; p = 0.010)." (PMID 38687739, 2024). "For example, Singh and colleagues discovered the expression of TAS2R4 differed between metastatic breast cancer and non-cancerous epithelial cell lines, and Gaida and colleagues demonstrated the expression and localization of TAS2R38 in a pancreatic cancer cell line." (PMID 28467517, 2017).
colorectal adenoma (3 papers, 2020 to 2024). An adenoma that arises from the colon or rectum. "A null association, similar to ours, was observed for TAS2R38 gene diplotypes and colorectal adenoma in a multiethnic population of Japanese American, whites and native Hawaiians." (PMID 38687739, 2024). "In a cohort study of colorectal adenoma cases, researchers explored the association between colorectal adenoma risk, dietary intake and genetic variation in three TAS2R genes: TAS2R38 (rs713598, rs1726866, rs10246939), TAS2R16 (rs846672) and TAS2R50 (rs1376251)." (PMID 32708215, 2020). "In contrast, in a multi-ethnic case–control study, neither the risk for developing colorectal adenoma nor most selected dietary variables were associated with several genetic variations of the bitter taste receptor genes TAS2R16, TAS2R38 and TAS2R50." (PMID 34885005, 2021).
pancreatic cancer (3 papers, 2017 to 2021). "The functionality of TAS2R38 and its co-location with lipid droplets was confirmed in a pancreatic cancer cell line and a pancreatic stellate cell line (RLT)." (PMID 34885005, 2021). "It was reported that TAS2R38 was expressed and localised intracellularly in lipid droplets of tumour cells from pancreatic cancer patients and tumour-derived cell lines." (PMID 32708215, 2020). "Controversially, the stimulation of TAS2R38 by PTC, as specific agonist of TAS2R38, or AHL-12, a bacterial molecule, induced the upregulation of the protein ABCB1, which fosters multidrug resistance in a pancreatic cancer cell line." (PMID 34885005, 2021).
periodontal disease (3 papers, 2021 to 2024). "Some studies regarding the same gene have indicated that the TAS2R38 genotype has a significant role in modulating the reaction of gingival epithelial cells to bacteria associated with both caries and periodontal disease." (PMID 38397921, 2024). "However, future research will be needed to confirm the association between clinical signs of periodontal disease and TAS2R38 genotype observed in the current study." (PMID 35090440, 2022). "Recent in vitro work has suggested that TAS2R38 genotype is important in mediating the response of gingival epithelial cells to bacteria involved in both caries and periodontal disease." (PMID 35090440, 2022).
rhinosinusitis (3 papers, 2016 to 2021). "The different genetic makeup of the populations studied in our work and in those by Adappa and colleagues is therefore to be considered when drawing inferences about TAS2R38 and rhinosinusitis." (PMID 27515546, 2016).
viral infection (3 papers, 2024). "Thus, it is conceivable that individuals who carry the same TAS2R38 diplotypes may exhibit common patterns in symptomatology arising from a broad range of viral infections, but further research is necessary to evaluate this." (PMID 38409357, 2024). "The relationship between TAS2R38 SNPs and viral infection, particularly that of SARS-CoV-2, has not been previously determined in PCD patients." (PMID 39201321, 2024).
colon cancer (2 papers, 2021 to 2024). "Utilizing univariate Cox regression analysis, we identified seven TAS2Rs genes associated with prognosis in colon cancer patients, including TAS2R4, TAS2R5, TAS2R14, TAS2R19, TAS2R20, TAS2R31, and TAS2R38." (PMID 38999959, 2024). "The results indicate a significantly elevated expression level of TAS2R38 in colon cancer tissues." (PMID 38999959, 2024). "Our results show that compared to normal colon tissue, the expression levels of multiple bitter taste receptor genes are elevated in colon cancer tissue, including TAS2R4, TAS2R5, TAS2R14, TAS2R19, TAS2R20, TAS2R31, and TAS2R38." (PMID 38999959, 2024). "Differential expression analysis results revealed that compared to normal colon tissue, colon cancer samples exhibited elevated expression levels of TAS2R1, TAS2R4, TAS2R5, TAS2R14, TAS2R19, TAS2R20, and TAS2R38 (p < 0.05), with the exception of TAS2R60, which was downregulated." (PMID 38999959, 2024).
diabetes (2 papers, 2023 to 2024). "A Sorbs cohort study consisting of populations from eastern Germany revealed a significant link between haplotypes of TAS2R38, the gene encoding a common bitter taste receptor, and parameters of glucose homeostasis in men without diabetes." (PMID 36768516, 2023).
inflammatory bowel disease (2 papers, 2021 to 2024). A spectrum of small and large bowel inflammatory diseases of unknown etiology. "Berberine, which acts as an agonist for TAS2R38 and TAS2R46, has the ability to decrease inflammatory reactions and has been used for a long time in treating inflammatory bowel disease." (PMID 38397921, 2024).
nasal polyps (2 papers, 2016 to 2024). "The distribution of the different genotypes at the TAS2R38 locus was not significantly different between CRS patients, either with or without nasal polyps, and controls." (PMID 27515546, 2016).
primary ciliary dyskinesia (2 papers, 2020 to 2024). A rare, genetically heterogeneous, primarily respiratory disorder characterized by chronic upper and lower respiratory tract disease. "In addition, the CRS genetic background can be linked with the genes associated with bacterial colonization, immunological processes in the body, primary ciliary dyskinesia (PCD), or taste receptor (T2R) genes (TAS2R38)." (PMID 33255995, 2020).
alcoholism (1 paper, 2017). "A possible link between this phenotype or TAS2R38 gene and alcoholism has been claimed." (PMID 29168731, 2017).
allergies (1 paper, 2024). "Due to the different molecular mechanisms of the immune response in allergies and the nasal mucosa protection properties of the TAS2R38 bitter taste receptor, this relationship may be difficult to determine and certainly requires further research." (PMID 38255273, 2024).